AXIN2 (axin 2)
Diseases named in the same sentence as AXIN2 in open-access papers (continued):
Sharing a sentence is not in itself a finding about the gene and the disease.
colon carcinoma (continued). "In HT29 colon cancer cells, mRNA expression of PLOD2, HADH and LCOR as well as AXIN2 as a canonical control target was downregulated upon treatment with the Porcupine inhibitor LGK974." (PMID 29453334, 2018). "In agreement with effects observed for colon cancer 16,17,20,21,40,44, we found that the TNKS-target AXIN2 was stabilized in all three OS lines evaluated." (PMID 24403055, 2014). "AXIN2, LEF1, TCF7, and PROX1 were highly expressed in colon cancer compared with control samples." (PMID 37584250, 2023). "Levels of WNT target gene mRNAs were markedly increased in colon tumor tissues compared with colon non-tumor tissues, especially Mmp7 and Axin2 mRNAs." (PMID 36765047, 2023). "The primary objective of this study was to assess whether pre-operative treatment with decitabine can decrease methylation and increase the expression of WNT target genes APCDD1, AXIN2 and DKK1 in colon cancer patients." (PMID 34068407, 2021). "Nevertheless, the finding is consistent with low levels of Axin2 and other Wnt target genes as well as the lack of APC mutation in MSI-H colon cancer cells with BRAF-V600E mutation." (PMID 31811196, 2019). "Remarkably, nearly all BRAF-V600E tumors had low expression of Axin2, RNF43, and ZNRF3, but not vice versa, consistent with previous report of low Wnt signaling in colon tumors with MSI-H BRAF-V600E mutation." (PMID 31811196, 2019). "In summary, our study demonstrates that CDX2 inhibits the proliferation and tumor formation of colon cancer cells by suppressing Wnt signaling activity and reveals a molecular mechanism by which CDX2 regulates the transcriptional activation of GSK-3β and Axin2." (PMID 30631044, 2019). "Consequently, the expression of several β-catenin target genes decreases, including Axin2, Lgr5, Cd44, Birc5, and c-myc, indicating that CCAR1 functions in the same way in gastric cancer cells as it does in colon carcinoma cells." (PMID 28230774, 2017). "Next, we examined whether Axin2 regulates TCF/LEF transcriptional activity and the Snail-mediated EMT program in colon cancer cells." (PMID 28418862, 2017). "Our results suggest that expanding of methylation in the promoter region of AXIN2 in SSAs lead to the suppression of the AXIN2 gene expression gradually, which contributes to a stepwise acquisition of the epigenetic features seen in MSI colon cancer." (PMID 24964857, 2014). "To further assess Wnt upregulation, we performed qRT-PCR analysis using total RNA isolated from the colonic tumors of APCMin and APC-Cldn1 and detected increased mRNA expression of the established Wnt-target genes CD44 (p = 0.0159), Lgr5 (5-fold increase), and Axin2 (3-fold increase)." (PMID 24997475, 2014). "Although not identified as a stem cell marker, Axin2 is an established target of Wnt signaling and contributes to colon cancer cell invasion." (PMID 24997475, 2014). "Finally, it was shown that the canonical WNT suppressor Axin 2 promotes colon carcinoma oncogenic activity rather than functioning as a tumor suppressor as expected." (PMID 26041882, 2015). "Other genes besides AXIN2, were identified that exhibit methylation profiles shared between SSA and MSI CRC and would be interesting to further investigate how these genes work and interact with each other during the progression of colon cancer of the serrated adenoma-MSI carcinoma sequence." (PMID 24964857, 2014). "FOXO1 inhibition impacted AXIN2, LEF1, and TCF7 in some, but not all, examined BBC and colon cancer cell lines." (PMID 37584250, 2023). "(H) qRT-PCR for Axin2, Ccnd1, Myc, and Ctnnb1 in HCT116 colon cancer cells treated with miR-31 inhibitor and negative control (NC, Scramble RNA), as well as miR-31 mimics and negative control (NC, Scramble RNA) for 24 hrs." (PMID 28870287, 2017). "In colon cancer, WNT2 might bind to FZD3 to upregulate AXIN2, as well as RNF43 for its negative feedback regulation, in which the modification and degradation of β-catenin are key pathway events in tumor progression." (PMID 39228892, 2024).
colon carcinoma (continued). "Furthermore, qRT-PCR analysis for Wnt target genes (including cMyc, Ascl2, Axin2, CD44, CD1, Sox17, Wif1 and Tiam1) did not identify any significant differences between the colonic tumours isolated from both cohorts of mice." (PMID 25881306, 2015).
breast cancer (55 papers, 2009 to 2026). A primary or metastatic malignant neoplasm involving the breast. "A polymerase chain reaction-restriction fragment length polymorphism (PCR-RFLP) assay was designed to genotype the AXIN2 rs2240308 C>T, rs1133683 C>T, rs7224837 A>G polymorphisms among 150 breast cancer patients and 150 healthy subjects." (PMID 34452579, 2021). "It has been suggested that polymorphisms at AXIN2 gene are associated with the risk of developing of breast cancer." (PMID 34452579, 2021). "Here, the authors aimed to evaluate the association between AXIN2 rs2240308 C>T, rs1133683 C>T, rs7224837 A>G polymorphisms with susceptibility to breast cancer." (PMID 34452579, 2021). "The AXIN2 gene locates at chromosome 17q23–24, which belongs to a heterozygosity region that frequently loss in neuroblastoma, breast cancer, and other cancers." (PMID 33794810, 2021). "There was one participant in the increased FH risk cohort that was found to carry a LP variant in AXIN2 and had a family history of breast cancer." (PMID 33413596, 2021). "Although numerous genetic association studies on breast cancer have been published, there are few a few studies about association of AXIN2 gene with breast cancer risk." (PMID 34452579, 2021). "The association between AXIN2 and breast cancer has been demonstrated in limited populations and their results were somewhat inconclusive." (PMID 34452579, 2021). "The present study aimed to evaluate the association between AXIN2 rs2240308 C>T, rs1133683 C>T, rs7224837 A>G polymorphisms with susceptibility to breast cancer." (PMID 34452579, 2021). "Deletion or deregulation of Axin2 is related to adrenal and breast cancers, and Axin2 gene polymorphism has been identified in lung cancer." (PMID 32486158, 2020). "Further, Myc (encoding c-Myc) and CCND1 (encoding Cyclin D1), AXIN2, etc. as canonical Wnt signaling targets were highly amplified in breast cancers." (PMID 31462314, 2019). "The axis inhibition protein 2 (AXIN2), a member of the WNT pathway, is associated with the development and progression of breast cancers, and polymorphisms in AXIN2 are associated with increased risk for breast cancer in premenopausal women." (PMID 28376813, 2017). "Polymorphisms in the AXIN2 gene, including rs11079571, have recently been shown to be associated with increased breast cancer risk, suggesting they play a role in cancer susceptibility." (PMID 24695522, 2014). "Except the SNP in β-catenin gene which was associated with increased risk of breast cancers, the other four SNPs in AXIN2, DKK3, SFRP3 and TCF7L2 genes were associated in a protective manner." (PMID 23516639, 2013). "Although, somatic mutations and epigenetic silencing of AXIN2 gene is uncommon in breast cancers, it has been reported in colorectal and lung cancers, respectively." (PMID 23516639, 2013). "We investigated four SNPs in AXIN2 gene to identify predisposition of breast cancers to any of these genetic variants." (PMID 23516639, 2013). "In breast cancer, we recently demonstrated that SNPs in the AXIN2 and APC genes are associated with risk." (PMID 19732438, 2009). "The AXIN2 polymorphisms have been associated with colorectal, lung, prostate, and breast cancer." (PMID 35996498, 2022). "Association of AXIN2 genotypes with clinical characteristics of breast cancer." (PMID 35996498, 2022). "However, there was one participant with a likely pathogenic AXIN2 variant and a family history of breast cancer—clinical evidence regarding this association is only emerging." (PMID 33413596, 2021). "In addition to the many AXIN2 mutations reported in various cancer types, a few reports have linked AXIN2 SNPs to the disease risk in breast cancer." (PMID 34452579, 2021). "Therefore, further studies in Iranian population should be conducted to explain the association between AXIN2 polymorphisms and breast cancer." (PMID 34452579, 2021).
breast cancer (continued). "Consistent with the idea that AXIN2 might act as a tumor suppressor, AXIN2 downregulation is associated with poorer overall survival of patients with breast cancer." (PMID 31382613, 2019). "Although the decreased risk of breast cancer with GG homozygosity compared with AA homozygosity in the AXIN2 rs3923087 was observed only in the younger patient cohort, the heterozygous AG genotype was associated with reduced risk in both the age groups as well as in the overall study." (PMID 23516639, 2013). "In particular, AXIN2 variants, which alter Wnt signaling, have been associated with an increased predisposition to colorectal and breast cancer, reinforcing the concept that dysregulation of developmental pathways may predispose individuals to both dental anomalies and oncogenesis." (PMID 41226524, 2025). "The impact of AXIN2 polymorphisms in the breast cancer development remains unclear." (PMID 34452579, 2021). "SAMD4B overexpression increased Topflash luciferase activity and upregulated the expression of β-catenin, Axin2, Cyclin D1, and c-Myc in breast cancer cells." (PMID 41154652, 2025). "Activated-β-catenin and AXIN2 mRNA levels are also increased in ER+ mouse mammary tumor cells expressing human PIK3CAH1047R compared with transgenic MMTV-Her2/neu mouse mammary tumor cells." (PMID 37471270, 2023). "Genotype, allele and haplotype frequencies of the AXIN2 and TCF7L2 polymorphisms in the breast cancer patients and control group." (PMID 35996498, 2022). "In conclusion, our study shows that the C/T and T/T genotypes of the AXIN2 rs2240308 variant and the TCF7L2 rs7903146 C/T and rs12255372 T/T genotypes are linked to breast cancer." (PMID 35996498, 2022). "Variants in AXIN2 and TCF7L2 in the Wnt-β catenin pathway have been associated with different types of cancer; however, little is known about its role in breast cancer." (PMID 35996498, 2022). "It has been described that genetic alterations in Wnt pathway components, such as APC, β-catenin, AXIN2, and TCF7L2 are implicated in colorectal, melanoma, gastric, hepatocellular, and breast cancer." (PMID 35996498, 2022). "Comparative analysis of the AXIN2 and TCF7L2 variants in breast cancer patients and the control group showed significant differences." (PMID 35996498, 2022). "Their results showed a significant association of genetic variants including AXIN2 rs3923087, β-catenin rs4135385, DKK3 rs6485350, SFRP3 rs7775 and TCF7L2 rs12255372 with breast cancer risk in the population." (PMID 34452579, 2021). "The frequencies of AXIN2 rs2240308 C>T, rs1133683 C>T, rs7224837 A>G genotypes were similar in breast cancer patients and controls." (PMID 34452579, 2021). "The results of real-time PCR showed that mRNA expression of Axin2 and Survivin was significantly decreased after gigantol treatment in breast cancer MDA-MB-231 and MDA-MB-468 cells." (PMID 29444668, 2018). "To further confirm the inhibitory effects of gigantol on Wnt/β-catenin signaling in breast cancer cells, we investigated the effect of gigantol on the expression of Axin2 and Survivin, both of which are well-known target genes in the Wnt/β-catenin pathway." (PMID 29444668, 2018). "The Wnt effector AXIN2 is upregulated in breast carcinoma and is involved in the Wnt-Axin2-GSK3beta cascade to regulate the epithelial–mesenchymal transition in breast cancer cells." (PMID 28929082, 2017). "Compared to MMTV‐Her‐2 transgenic mouse mammary tumors, H1047R tumors showed increased upregulation of Wnt/β‐catenin/Axin2, hepatocyte growth factor (Hgf)/Stat3, insulin‐like growth factor 2 (Igf‐2), and Igf‐1R pathways." (PMID 28296140, 2017). "Our results also suggested Smad7 to be the target of SOX7 and AXIN2 in controlling breast cancer progression through the Wnt/β-catenin signaling pathway." (PMID 27188720, 2016). "We found that the expression of SOX7 was significantly reduced in breast cancer and this effect was positively correlated with AXIN2." (PMID 27188720, 2016).
breast cancer (continued). "Our results also showed Smad7 as the target of SOX7 and AXIN2 in controlling breast cancer progression through the Wnt/β-catenin signaling pathway." (PMID 27188720, 2016). "Axin2 can regulate epithelial-mesenchymal transition by controlling Snail1 activity in breast cancer cells and its expression has been shown to be upregulated in breast tumours." (PMID 24178749, 2014). "We observed statistically significant association of SNPs in β-catenin (rs4135385), AXIN2 (rs3923087), DKK3 (rs6485350), SFRP3 (rs7775) and TCF7L2 (rs12255372) genes with breast cancer risk." (PMID 23516639, 2013). "Genetic variants in AXIN2, DKK3, SFRP3 and TCF7L2 were associated with reduced risk of breast cancer." (PMID 23516639, 2013). "We also contrasted the expression of both β-CATENIN [i.e. non-phospho (active) β-catenin (SER33/37/Thr41) vs. a pan-β-catenin-antibody] and AXIN2 in TNBC with other breast cancer subtypes (ER+, PR+, HER2+ and TP+)." (PMID 23307470, 2013). "Kindlin 2– β-catenin complex was originally confirmed in breast cancer cells, in which Kindlin 2 was recruited by β-catenin to activate Wnt target gene AXIN2, and, in turn, promote the EMT process." (PMID 23717433, 2013). "Genotypic analysis of individual locus showed statistically significant association of five SNPs located in β-catenin, AXIN2, DKK3, SFRP3 and TCF7L2 with breast cancers." (PMID 23516639, 2013). "The AXIN2 rs3923087, DKK3 rs6485350 and the SFRP3 rs7775 that was significantly associated with decreased risk of breast cancer in the overall study population also exhibited significant protection for the ER + as well as ER- group." (PMID 23516639, 2013). "We show that application of the small molecule tankyrase inhibitor, XAV939 or siRNA-mediated abrogation of tankyrase expression increases Axin1 and Axin2 protein levels and attenuates Wnt-induced transcriptional responses in several breast cancer lines." (PMID 23144924, 2012). "PIK3CA mutant ER+ breast cancers exhibit an RNA expression profile of enhanced Wnt/β-catenin signaling, including up-regulation of Wnt target genes (AXIN2, LEF1, MYCN) and other components such as transcriptional regulators (TCF7L1, TCF7L2, CTNNB1), receptors (FZD4, FZD7) and ligands (WNT5A)." (PMID 37471270, 2023). "This study tests the hypothesis of links between AXIN2 rs1133683 and rs2240308, and TCF7L2 rs7903146 and rs12255372 variants in breast cancer." (PMID 35996498, 2022). "We hypothesis that the distribution of alleles, genotypes, and haplotypes of the rs1133683 and rs2240308 variants of the AXIN2, and the rs7903146 and rs12255372 variants of the TCF7L2, are linked to major clinicopathological characteristics of breast cancer." (PMID 35996498, 2022). "In conclusion, this case-control study indicated that AXIN2 rs2240308, rs7224837 and rs1133683 polymorphisms did not contribute to increased risk of breast cancer." (PMID 34452579, 2021). "This study results revealed that AXIN2 rs2240308, rs7224837 and rs1133683 polymorphisms did not contribute to increased risk of breast cancer." (PMID 34452579, 2021). "Our results indicated that AXIN2 rs2240308, rs7224837 and rs1133683 polymorphisms did not contribute to increased risk of breast cancer." (PMID 34452579, 2021). "Furthermore, the Wnt/β-catenin target gene AXIN2 contributes to Snail1 protein stabilization in breast cancer cells by regulating GSK-3β localization." (PMID 33227961, 2020). "Although Wnt signaling was first described as inducing breast tumors in mice and Wnt/β-catenin signaling is activated in a proportion of multiple subtypes of human breast cancers, the typical mutations in components of the pathway found in CRC (APC, CTNNB1, AXIN2) are rare in breast carcinomas." (PMID 33227961, 2020). "However, YAP has also been observed to restrain AXIN2 transcription in mouse embryonic stem cells and MCF-10 breast cancer cells, which is in line with the mild induction of AXIN2 transcription in HCT-15 cells upon YAP1 KD." (PMID 30717152, 2019).